ELP1 (elongator acetyltransferase complex subunit 1)
Description:
Component of the elongator complex which is required for multiple tRNA modifications, including mcm5U (5-methoxycarbonylmethyl uridine), mcm5s2U (5-methoxycarbonylmethyl-2-thiouridine), and ncm5U (5-carbamoylmethyl uridine). The elongator complex catalyzes the formation of carboxymethyluridine in the wobble base at position 34 in tRNAs. Regulates the migration and branching of projection neurons in the developing cerebral cortex, through a process depending on alpha-tubulin acetylation (By similarity). ELP1 binds to tRNA, mediating interaction of the elongator complex with tRNA (By similarity). May act as a scaffold protein that assembles active IKK-MAP3K14 complexes (IKKA, IKKB and MAP3K14/NIK).
Synonyms: IKAP; IKBKAP; TOT1; IKI3; DYS; FD
Tractability: Small molecule: a structure with a bound ligand is known. PROTAC: ubiquitination databases record sites on it.
Target class: Kinase; Protein kinase regulatory subunit; Enzyme
Gene: Protein-coding gene on chromosome 9 (108,866,898 to 108,934,414, reverse strand). Ensembl gene ENSG00000070061.
Subcellular location: Cytoplasm; Nucleus
Subcellular location (Human Protein Atlas): Cytosol; Nucleoplasm
Pathways (Reactome):
Chromatin organization: HATs acetylate histones
Gene Ontology:
Molecular function: protein binding; tRNA binding
Biological process: regulation of translation; tRNA wobble base 5-methoxycarbonylmethyl-2-thiouridinylation; tRNA wobble uridine modification
Cellular component: cytoplasm; cytosol; elongator holoenzyme complex; nucleoplasm; nucleus
Genetic constraint (gnomAD): Loss-of-function variants: 105 observed, 153.77 expected, observed/expected ratio (o/e) 0.68, 90% interval 0.58 to 0.8. The upper end of that interval is the gene's LOEUF score, 0.8, which puts it in group 3 of 6, group 1 being the genes least tolerant of losing a copy. Missense variants: 1,422 observed, 1,526.9 expected, observed/expected ratio (o/e) 0.93, 90% interval 0.89 to 0.97. Synonymous variants: 510 observed, 559.35 expected, observed/expected ratio (o/e) 0.91, 90% interval 0.85 to 0.98.
Gene-disease validity (ClinGen):
ClinGen rates the evidence that ELP1 causes each of these diseases.
Riley-Day syndrome (autosomal recessive): Moderate.
Homologues: Orthologues: chimpanzee ELP1 (99% identical), macaque ELP1 (96% identical), dog ELP1 (89% identical), pig ELP1 (88% identical), guinea pig ELP1 (85% identical), rat Elp1 (82% identical), mouse Elp1 (81% identical), rabbit ELP1 (81% identical), tropical clawed frog elp1 (61% identical), zebrafish elp1 (58% identical), Drosophila melanogaster Elp1 (31% identical), Caenorhabditis elegans elpc-1 (20% identical).
Diseases named in the same sentence as ELP1 in open-access papers:
ELP1 is named in the same sentence as 64 diseases in open-access papers, as found by Europe PMC text mining. Sharing a sentence is not in itself a finding about the gene and the disease. The quoted sentences say what the papers report.
Familial dysautonomia (50 papers, 2009 to 2026). "Familial dysautonomia (FD) is a rare genetic, neurodevelopmental and neurodegenerative disorder, where a homozygous mutation in the ELP1 gene is responsible for defects and symptoms found in 99% of patients." (PMID 41041527, 2025). "Mutations in ELP1 cause familial dysautonomia (FD), a fatal disorder characterized by the presence of smaller trigeminal nerves and sensory deficits." (PMID 39381860, 2024). "Familial dysautonomia (FD) is a rare recessive neurodevelopmental disease caused by a splice mutation in the Elongator acetyltransferase complex subunit 1 (ELP1) gene." (PMID 38177237, 2024). "For example, mutations in ELP1 cause familial dysautonomia (FD), a neurodevelopmental and neurodegenerative disease." (PMID 39381860, 2024). "In contrast to the multifactorial origin of these neurological diseases, neurodevelopmental impairment and neurodegeneration in Familial Dysautonomia (FD) results from a single point mutation in the ELP1 gene." (PMID 36984872, 2023). "Familial dysautonomia (FD) is a rare neurodevelopmental and neurodegenerative disease caused by a splicing mutation in the Elongator Acetyltransferase Complex Subunit 1 (ELP1) gene." (PMID 37903840, 2023). "Studies of a predominantly autonomic nervous system (ANS) disorder, familial dysautonomia (FD), have identified a missense mutation in the ELP1 gene resulting in an exome skipping event leading to the tissue-specific manner depletion of the gene product." (PMID 36864284, 2023). "Familial dysautonomia (FD) is a sensory and autonomic neuropathy caused by mutations in elongator complex protein 1 (ELP1)." (PMID 35713404, 2022). "The most prevalent form is HSAN type III, or familial dysautonomia (FD), which is almost exclusively caused by a mutation in intron 20 of the elongator complex protein 1 (ELP1, formerly IKBKAP) gene." (PMID 35713404, 2022). "In humans, mutation of the gene coding for ELP1, underlies Familial dysautonomia (FD), a devastating disease that mostly affects the development and survival of neurons from the autonomic nervous systems." (PMID 34620845, 2021). "Remarkably, comparable defects occur in fibroblasts from Familial Dysautonomia (FD) patients bearing an autosomal recessive mutation in the gene coding for the Elongator subunit ELP1." (PMID 34620845, 2021). "ELP1 is associated with familial dysautonomia, a neurodevelopmental disorder that affects the sensory and autonomic nervous system." (PMID 31213517, 2019). "At the genetic level, Riley-Day syndrome otherwise known as familial dysautonomia is a rare hereditary autonomic neuropathy caused in the majority of cases by a mutation in the IKBKAP/ELP1 gene." (PMID 30064458, 2018). "Multiple studies in a variety of model organisms, as well as in brain tissue and fibroblasts from patients with familial dysautonomia (FD) that carry mutations in IKBKAP/ELP1, have shown that Elongator is essential for the synthesis of the mcm5 modification." (PMID 29497044, 2018). "Familial dysautonomia (FD) results from mutation in IKBKAP/ELP1, a gene encoding the scaffolding protein for the Elongator complex." (PMID 29497044, 2018). "Familial dysautonomia (FD; also called Riley–Day syndrome) is a fatal autosomal recessive neurodegenerative disorder that is caused by an intronic mutation in IKBKAP/Elp1, the gene for inhibitor of kappa B kinase complex-associated protein (IKAP)." (PMID 27699209, 2016). "Elongator in higher eukaryotes is required for normal growth and development and a mutation in the largest subunit of human Elongator (Elp1) causes familial dysautonomia, a severe recessive neuropathy." (PMID 24750273, 2014). "It is interesting to note that mutations in the human ELP1 gene, also called IKBKAP, cause the neurodegenerative disease, Familial Dysautonomia (FD)." (PMID 19593383, 2009).
Familial dysautonomia (continued). "Mutations in the human homologue of yeast ELP1, IKBKAP/hELP1, have been shown to cause Familial Dysautonomia (FD), a genetic disorder primarily affecting the sensory and autonomic nerve systems." (PMID 19593383, 2009). "We first made use of human primary fibroblasts derived from patients affected by Familial Dysautonomia (FD), a condition characterized by the loss of Elp1 expression (IKBKAP-/-), a key component of the Elongator complex essential for the biosynthesis of mcm5s2U-modified tRNA." (PMID 40806605, 2025). "Familial Dysautonomia (FD) is a rare disease caused by ELP1 exon 20 skipping." (PMID 38829854, 2024). "Mutations in the donor splice site of intron 20 of ELP1/IKBKAP gene (an Elongator complex subunit) have been linked to familial dysautonomia (FD), a hereditary genetic disorder characterized by improper development and function of the sensorial and autonomic nerve systems." (PMID 30477220, 2018). "Mutations in the human IKBKAP/ELP1 gene, resulting in severely reduced IKAP/ELP1 protein levels in the nervous system, cause the autosomal-recessive neurodevelopmental disorder—familial dysautonomia (FD)." (PMID 34819065, 2021). "HSAN type III, known as familial dysautonomia (FD), results from a single base mutation in the gene IKBKAP that encodes a scaffolding unit (ELP1) for a multi-subunit complex known as Elongator." (PMID 28167615, 2017). "Familial Dysautonomia (FD, OMIM #223900) is a rare, life-threatening autosomal recessive neuropathy caused in 99.8% of patients by the c.2204 + 6T > C intronic mutation in the ELP1/IKAP gene." (PMID 41964038, 2026). "Familial dysautonomia (FD), also referred to as hereditary sensory and autonomic neuropathy type III, is a devastating rare genetic neuropathy that results from mutations in the gene ELP1 (previously referred to as IKBKAP)." (PMID 35481599, 2022). "Familial dysautonomia (FD) is a rare neurodegenerative disease caused by a mutation in intron 20 of the IKBKAP gene (c.2204+6T>C), leading to tissue-specific skipping of exon 20 and a decrease in the synthesis of the encoded protein IKAP (also known as ELP1)." (PMID 27483351, 2016). "Hereditary sensory and autonomic neuropathy type III (HSAN type III) results from an autosomal recessive genetic mutation on chromosome 9q that causes a deficiency of IκB kinase complex‐associated protein (IKBKAP), leading to a reduction in expression of elongator complex protein 1 (ELP‐1)." (PMID 37029664, 2024). "Familial dysautonomia (FD; MIM223900) is an autosomal recessive congenital neuropathy that is caused by an intronic mutation in the IKBKAP gene, which encodes the inhibitor of κB kinase complex-associated protein (IKAP), also called elongator complex protein 1 (ELP1)." (PMID 29929962, 2018). "Interestingly, a truncated version of elpc-1 (which resembles the ELP1 mutation present in patients suffering from Familial Dysautonomia (FD), was not able to rescue even though its localization in the cytoplasm was unaffected by the truncation (data not shown)." (PMID 20107598, 2010).
medulloblastoma (16 papers, 2021 to 2026). A malignant, invasive embryonal neoplasm arising from the cerebellum. "In medulloblastoma, the loss of mutations in Elp1 can cause instability of the Elongator complex, loss of tRNA modifications, and trigger codon-dependent translational reprogramming and unfolded protein responses." (PMID 41501031, 2026). "In pediatric medulloblastoma, germline mutations in Elp1 and sustained activation of the Sonic Hedgehog signaling pathway increase patient susceptibility to disease." (PMID 41501031, 2026). "The consistent prevalence of P/LP variants in ELP1 in multiple cohorts provides supportive evidence for adding ELP1 to cancer susceptibility gene lists, especially for medulloblastoma." (PMID 39184053, 2024). "Germline loss-of-function (LOF) variants in ELP1 have recently been strongly associated with medulloblastoma in pediatric age, predisposing a patient to tumor development in combination with constitutive activation of Sonic Hedgehog (SHH) signaling." (PMID 38139220, 2023). "In conclusion, the absolute risk of developing childhood medulloblastoma with ELP1 and GPR161 appears low and families can be reassured particularly if these genes are found incidentally on panels." (PMID 36961676, 2023). "Recent genetic sequencing studies in large series’ of predominantly childhood medulloblastoma have implicated loss-of-function, predominantly truncating, variants in the ELP1 and GPR161 genes in causation of the MBSHH subtype specifically." (PMID 36961676, 2023). "ELP1 was also found to be the most common medulloblastoma predisposition gene as a number of germline LoF mutations were identified in the patients with this type of pediatric brain cancer." (PMID 36864284, 2023). "Loss of ELP5 and ELP1 has been demonstrated to directly impede the wobble U34 tRNA modification leading to cancer of the gallbladder and medulloblastoma respectively." (PMID 36448458, 2023). "Neither paper attempted to assess the overall likelihood of a child with either an ELP1 or GPR161 loss-of-function variants developing medulloblastoma." (PMID 36961676, 2023). "Based on this mouse model, they hypothesized that single-copy loss of ELP1 is key to understanding the medulloblastoma predisposition phenotype." (PMID 40471378, 2025). "The risks for siblings of medulloblastoma cases who are heterozygotes may still justify closer monitoring especially for ELP1 as the family may carry additional genetic factors that predispose to medulloblastoma." (PMID 36961676, 2023). "Mutations in the Elongator’s largest subunit ELP1 have been characterized in FD and medulloblastoma, and the data presented here represent the first report of a mutation in this gene found in patients with NDDs that primarily perturb the development of the CNS." (PMID 36864284, 2023). "Also, in pediatric SHH-medulloblastoma, germline alterations of the ELP1 gene have been described in 14% of cases, making this gene the most frequent genetic predisposition in medulloblastoma." (PMID 38139220, 2023). "Heterozygous mutations in ELP1, encoding the scaffolding subunit of the Elongator complex, accounts for nearly 15% of total hereditary predisposition to SHH-medulloblastoma." (PMID 40471378, 2025).
medulloblastoma (continued). "The CSGs with the most P/LP variants in cases, and significantly higher than controls, were the known medulloblastoma genes ELP1 and SUFU." (PMID 39184053, 2024). "ELP1 is a subunit of the elongator complex and was recently discovered to be pathogenic for SHH medulloblastoma, while other subunits have previously been linked with other cancers such as breast cancer and melanoma." (PMID 39184053, 2024). "The implied likelihood of developing medulloblastoma for both ELP1 and particularly GPR161 are overall quite low and at or well below that of PTCH1 for which no screening in childhood for medulloblastoma is recommended." (PMID 36961676, 2023). "Tumours from patients with ELP1 LoF medulloblastoma were characterized by codon‐dependent translational reprogramming and induction of the UPR and loss of protein homeostasis." (PMID 36448458, 2023). "The ELP1-medulloblastoma syndrome is caused by heterozygous pathogenic germline variants in the ELP1 gene and characterized by an increased risk of sonic hedgehog (SHH)-activated medulloblastoma during childhood." (PMID 35969220, 2022). "Absence of the ELP1 gene and protein expression in resected tumor material allows for the identification of patients with the ELP1-medulloblastoma syndrome." (PMID 35969220, 2022). "Therefore, they removed both copies of Elp1 from the cell-of-origin for SHH-medulloblastoma, the granule cell progenitor, using Atoh1-Cre mouse line (Elp1cKO)." (PMID 40471378, 2025). "ELP1 pathogenic variants (PV) have been recently identified as the most frequent variants predisposing to Sonic Hedgehog (SHH) medulloblastomas (MB); however, guidelines are still lacking for genetic counseling in this new syndrome." (PMID 38962751, 2024). "We identified P/LP variants in four of the six medulloblastoma genes: APC, ELP1, GPR161, and SUFU." (PMID 39184053, 2024). "However, as all but one of the cases was in the MBSHH subtype and the frequency in non SHH pathway medulloblastoma for ELP1 was only 1/542 (0.18%), similar to the 0.1% frequency in controls, we have assumed that all of the risk related to the MBSHH subtype." (PMID 36961676, 2023).
neuroblastoma (6 papers, 2012 to 2022). Neuroblastoma (NB) is the most common solid, extracranial childhood tumor. "The level of acetylated Tau, measured as ac-lysine levels above total Tau levels, was reduced in Elp1 KD neuroblastoma cells, as compared to control cells." (PMID 36393857, 2022). "For this, we incubated CoA and citrate (Acly substrates) with extracts from Elp1 KD and control neuroblastoma cells." (PMID 36393857, 2022). "For these experiments, we extracted protein from Elp1 KD and control neuroblastoma cells, immunoprecipitated Tau using specific antibodies and revealed by western blot using anti-pan acetyl lysine antibodies." (PMID 36393857, 2022). "Our results show in differentiated Elp1 KD neuroblastoma cells that Tau instability results from its hypoacetylation, which in turn increases its UPS degradation." (PMID 36393857, 2022). "Western blot analysis on protein extracts obtained from differentiated control and Elp1 KD neuroblastoma cells shows a reduction by almost 60% of Tau protein level in Elp1 KD, as compared to control cells." (PMID 36393857, 2022). "Quantitative analysis of Tau fluorescence intensity in differentiated cells shows that Tau levels in control neuroblastoma cells both before and after differentiation (respectively) are higher compared to Elp1 KD (respectively)." (PMID 36393857, 2022). "Here, by combining cellular and molecular analyses in a neuroblastoma cell line depleted for Elp1 and also in several Elp3 depletion models in vitro and in vivo we show that loss of Elongator results in reduced Tau protein levels." (PMID 36393857, 2022). "To investigate further and quantify the morphological differences previously observed between Elp1 KD and control neuroblastoma cells we applied live fluorescence microscopy image high content analysis (HCA) of Calcein AM live stained cells to visualize neurite morphologies." (PMID 36393857, 2022). "We observed a reduction of Acly protein expression levels also in our Elp1 KD neuroblastoma model." (PMID 36393857, 2022). "To assess that the hypoacetylation observed in both Tau and α-tubulin in Elp1 KD neuroblastoma model is caused by lack of acetyl-CoA; the acetyltransferase’s substrate, we conducted an in vitro α-tubulin acetylation assay." (PMID 36393857, 2022). "The severe reduction of Tau protein upon Elp1 deficiency is not exclusive to Elp1 KD neuroblastoma cells and is further supported in vivo in Elongator deficiency neuronal models in mice and flies." (PMID 36393857, 2022). "Indeed, we show that Cx43 acetylation is reduced in the cortex of Elp3cKO embryos, as well as in a neuroblastoma cell line depleted of Elp1 expression, suggesting that Cx43 acetylation requires Elongator in different cellular contexts." (PMID 28507509, 2017).
dysautonomia (4 papers, 2013 to 2020). An acute or chronic disorder, affecting the sympathetic or parasympathetic nervous system. "Familial dysautonomia is an autosomal recessive congenital neuropathy caused by an intronic mutation in IKBKAP, which encodes the protein IKAP (also known as ELP1)." (PMID 27699209, 2016).
Intellectual disability (4 papers, 2018 to 2023). "We report a novel missense mutation in the ELP1 identified in two siblings with intellectual disability and global developmental delay." (PMID 36864284, 2023). "Studies on the IKBKAP/ELP1 gene pathway have indicated its role in neurological disorders such as those related to intellectual disability, epilepsy and amyotrophic lateral sclerosis." (PMID 30064458, 2018).